MYC (MYC proto-oncogene, bHLH transcription factor)
Diseases named in the same sentence as MYC in open-access papers (continued):
Sharing a sentence is not in itself a finding about the gene and the disease.
multiple myeloma (continued). "Of note, none of the stable myeloma precursor condition cases had any SVs involving the MYC/PVT1 hotspot in sharp contrast with 35% (6/17) in progressive precursor condition cases and 32/80 (40%) MM (Fisher’s exact test p = 0.03 and p = 0.003, respectively)." (PMID 33767199, 2021). "Given that MYC promotes global protein synthesis and drives malignant transformation in the Vκ*MYC model, it is tempting to speculate that there is a functional interaction between MYC and GCN2 in myeloma." (PMID 34732728, 2021). "Additionally, in acute myeloma cells, it has been revealed that the lncRNA CCAT1 binds to miR-155, which leads to an increase in the level of MYC expression." (PMID 34440124, 2021). "Vk*MYC treated mice had a clear M-spike (an indicator of multiple myeloma - MM), WT mice had a weaker M-spike and no M-spike was detected in untreated animals regardless of genetics." (PMID 32050978, 2020). "This suggests that MYC cannot initiate MGUS, but facilitates MGUS progression to myeloma." (PMID 31231360, 2019). "Compared to RPMI8226, a multiple myeloma cell line that relies on c-MYC for survival, we failed to observe suppression of c-MYC protein levels following bortezomib or MLN2238 treatment." (PMID 30860482, 2019). "To identify genes that are inhibited by CBL0137 similarly to MYC, we analyzed the effect of CBL0137 on the gene expression profiles of two human tumor cell lines, namely multiple myeloma MM1.S and fibrosarcoma HT1080 using microarray hybridization and nascent RNA-sequencing." (PMID 30926878, 2019). "Unfortunately, data on MYC rearrangements were not available for patients at diagnosis and evidence for inclusion of 1q21 gain was lacking when Myeloma X was designed, both of which would further the relevance of our findings." (PMID 30729512, 2019). "In this study, we report the discovery of a drug-like compound with dramatic effects on MYC expression in multiple myeloma cells, demonstrate that it acts by a G4-dependent mechanism of action, and solve a complete structure by NMR of the compound in complex with the MYC G4." (PMID 30315240, 2018). "In myeloma cells, this mechanism is described as an autoregulatory circuit, with IRF4 directly targeting MYC and at the same time IRF4 representing a direct target of MYC transactivation." (PMID 29617304, 2018). "We demonstrated that PGG inhibited the MYC and DEPTOR expression in myeloma cells." (PMID 29472861, 2018). "Our data suggest that CBP/EP300 bromodomain inhibition exerts its anti-myeloma effects in a mechanism distinct from BET inhibition via the direct transcriptional inhibition of IRF4 and the downstream suppression of IRF4 target genes such as MYC." (PMID 26731516, 2016). "CBP/EP300 bromodomain inhibition thus targets the IRF4/MYC network, which is critical for multiple myeloma cells independent of the upstream oncogenic signal." (PMID 26731516, 2016). "However, while several MYC signatures were also enriched upon treatment with SGC-CBP30, more notable was the enrichment of signatures for pathways important in multiple myeloma, which was distinct from the effects of BET inhibition." (PMID 26731516, 2016). "Interestingly, we originally compared MYC mRNA levels in cell lines and primary cells applying GAPDH mRNA as the only reference, getting higher MYC levels in primary cells than in myeloma cell lines." (PMID 26087190, 2015). "In multiple myeloma, which is characterized by chromosomal aberrations including MYC amplification, JQ1 showed significant effects in abrogating MYC oncogenic function and also reduced MYC expression." (PMID 23373009, 2013). "Accordingly, myeloma patient samples were shown to present a significantly higher expression of both MYC and IRF4 mRNA as compared to the normal plasma cells, thus further suggesting the existence of a positive correlation between IRF4 and MYC expression levels in MM." (PMID 39482742, 2024).
multiple myeloma (continued). "Thus, a class switch strategy targeting the c-MYC gene and STAT3 activation via IL-6 with PI-containing therapy may be a reasonable option for LEN-refractory myeloma." (PMID 38004369, 2023). "In contrast, POM can suppress the c-MYC gene via proteasome-dependent degradation of AT-rich interaction domain 2 (ARID2), which is not a target molecule of LEN, suggesting that POM might be effective for a part of LEN-resistant myeloma cells." (PMID 38004369, 2023). "JQ1, a small molecule inhibitor of BET proteins, suppressed MYC expression in preclinical models of multiple myeloma (MM) and AML, effectively halting cancer growth in vitro and in vivo, although these and other studies indicated that BRD4 inhibition has multiple consequences beyond MYC inhibition." (PMID 36214609, 2022). "In conclusion, although TAK1-inhibitors might prolong survival somewhat, they do not prevent disease in the Vκ*MYC mouse model of multiple myeloma." (PMID 36435864, 2022). "However, several of our findings support that activation of the ISR-GCN2 pathway is not directly regulated by MYC in the Vκ*MYC model and human myeloma." (PMID 34732728, 2021). "Nonetheless, we found that Vκ*MYC tumours are comprised of 4–8 distinct subpopulations of malignant cells when defined using inferred CNV profiles, which is consistent with previous whole-exome sequencing and single-cell genetic analyses that uncover evidence for 2–6 subclones at myeloma diagnosis." (PMID 34732728, 2021). "Since Vk*MYC mice undergoing IAP inhibition responded to CPI with increased survival, in-depth analysis of that response may provide clues for how to incorporate CPI in human myeloma treatment protocols." (PMID 34149703, 2021). "Taken together, these data suggest that the bromodomains of CBP and EP300 are involved in the regulation of the IRF4/MYC axis in multiple myeloma cells, and the suppression of the IRF4/MYC axis may be important for the phenotypic effects of CBP/EP300 bromodomain inhibition." (PMID 26731516, 2016). "Thus, in contrast to myeloma cell lines, MYC levels in primary cells apparently are not determined by the number of gene copies as measured here, but by other mechanisms." (PMID 26087190, 2015). "As MYC activation and chromosome 13 deletion are considered early events likely to play a role in disease transformation from MGUS to MM, it suggests that different genetic subtypes of myeloma may have different requirements for transformation." (PMID 25101266, 2014). "Interestingly, while chr12q24 gains are not present in myeloma, we identified here a significant enrichment of c-MYC/MAX target genes in MM patients characterized by high SETD8 expression, thereby supporting a potential role of this oncogenic pathway in SETD8 deregulation." (PMID 34530900, 2021). "However, previous multiple myeloma fusion studies hypothesized that MYC fusions with Ig would not be detected from RNA-seq if there were no hybrid transcript generated after the translocation." (PMID 32471990, 2020). "Functionally, VitD3 and the EB-1089 analogue can reduce growth, inhibit MYC expression and increase CD38 expression by 50-400% on ABC-DLBCL and myeloma but not GC-DLBCL cells." (PMID 41884528, 2026). "The data also rules out abnormalities involving MAF, MAFB, MYC or NSD2/FGFR3, which are chromosomal translocations clinically relevant for multiple myeloma diagnosis." (PMID 40027317, 2024). "Lack of CD226 reduced the anti-myeloma response of NK and CD8 T cells, resulting in quicker tumor progression and decreased overall survival of Vκ*MYC mice." (PMID 34149703, 2021).
multiple myeloma (continued). "The C-MYC- expressing myeloma cell lines are inhibited by I-BET51, which exerts its inhibitory activity by diminishing the c-MYC expression, but in U266 cells that do not express c-MYC, I-BET151 interferes with MYCL expression." (PMID 34540687, 2021). "As suggested by the MYC analysis, t(IgL) patients experienced a worse PFS and OS as compared to non-t(IgL) myeloma." (PMID 31015454, 2019). "Compound 10058-F4, an inhibitor of MYC-MAX heterodimerization, induced apoptosis in primary myeloma clones, but not in U266 MM cells." (PMID 30068698, 2018). "We hypothesize that this lack of correlation arises because MMP13 in myeloma cells is primarily induced by CXCL7, whereas MYC, involved in various cancer pathways, is regulated by multiple mechanisms." (PMID 39915476, 2025). "As the role of IL-5 as growth factor for myeloma plasma cells is debated, and IL-5 should not impact on BM stromal cells, one mechanism by which anti-IL17, anti-IL-17RA, and anti-IL5 antibodies acted in Vk*MYC mice is a reduced accrual and survival of eosinophils and consequently of Th17 cells." (PMID 30510245, 2018). "Notably, MYC signature scores determined for each HMCL did not correlate with GCN2iB response (R = −0.067, P = 0.829) or ISR-GCN2 activity (R = 0.077, P = 0.802), suggesting that ISR-GCN2 activation may not be uniquely related to MYC dysregulation in human myeloma." (PMID 34732728, 2021).
melanoma (332 papers, 2005 to 2026). A malignant, usually aggressive tumor composed of atypical, neoplastic melanocytes. "The T-cell-induced IFN-γ gene signature accompanying the downregulation of wingless-type (WNT) and MYC signaling in melanoma is associated with a better response of melanoma patients to ICIs." (PMID 40108693, 2025). "We reveal that human DANCR is regulated by the cancer causing MITF and c-MYC transcription factors in melanoma, promotes human melanoma cell proliferation and migration and is associated with poor patient survival." (PMID 41336739, 2025). "A defining feature of BRAF-mutant melanoma is the upregulation of proliferation-associated genes, such as MYC, CCND1, and E2F1, which synergistically fuel the unchecked growth of melanoma cells." (PMID 40872623, 2025). "Transcriptomic datasets associated HS1 expression with activation of MYC signaling and cell cycle progression, and functional assays further confirmed its role in promoting malignant behavior in melanoma." (PMID 41441975, 2025). "Since downregulation of MYC was identified as an ICI-responsive alteration in melanoma cells, overexpression of MYC in melanoma cells was associated with resistance to anti-PD-1 immunotherapy." (PMID 40108693, 2025). "Altogether, our tool suggests favorable outcome is linked with immune activation while highlighting the possibility of MYC-driven immune suppression in high-risk melanoma patients." (PMID 37380943, 2023). "MYC has been proved to be a convergent downstream effector of resistance in melanoma caused by the reactivation of such pathways as ERK, PI3K, NOTCH1, and others." (PMID 35565444, 2022). "Overall, 22q11.21-amplified melanomas were significantly enriched in canonical signaling pathways associated with tumorigenesis and metabolic activity, including MYC target genes, oxidative phosphorylation, and unfolded protein response." (PMID 35197475, 2022). "MYC amplification was one of the most commonly detected CNVs, other frequent CNVs in mucosal melanoma included NBN and KDR, which were associated with the poor survival of melanoma patients." (PMID 35688842, 2022). "Copy number variants, including loss of CDKN2A and gain of KIT, CDK4 and MYC, were frequently seen in mucosal melanomas." (PMID 34571863, 2021). "For many years, c-MYC has been implicated in the development of numerous cancer types, including melanoma." (PMID 35048028, 2021). "Our results revealed that most RMM patients have CNVs mutations, and MYC was most frequently amplified, which was consistent with previous melanoma studies." (PMID 34044811, 2021). "IPA exploration of the gene network indicated the connection of SIRT3 modulated genes along with several melanoma-associated genes (MYC, PI3K, AKT, CD3, ERK, and AMPK)." (PMID 33937086, 2021). "Psen2 encodes the protein presenilin-2, a MYC target increased in melanoma cells, whereas Mapkapk3 is a member of the p38 pathway that promotes autophagy." (PMID 32831131, 2020). "Since then, genetic analysis showed an atypicalG464E mutation in the BRAF P loop region, accompanied by an enhancing G12D KRAS common oncogenic mutation which adds to higher c-MYC expression in C8161 melanoma compared to A375 cells." (PMID 30792807, 2019). "Well-studied in melanoma, c-MYC is implicated in more aggressive vertical growth phase melanomas and progression to metastasis." (PMID 31861163, 2019). "For instance, amplification of the MYC oncogene has been long associated with poor-outcome in Melanoma patients." (PMID 29666373, 2018). "Sirt1 stable silencing increased Mxd1 mRNA expression and led to down-regulation of MYC targets, such as Cdkn1a, Bcl2 and Psen2, whose upregulation is associated with human melanoma aggressiveness and poor prognosis." (PMID 29383100, 2017). "Overexpression, Mutations, translocation and rearrangement of MYC is related to several cancers such as breast, PCa, gastrointestinal, melanoma, and small cell lung cancer." (PMID 28651018, 2017).
melanoma (continued). "Many of these genes have previously been implicated in melanoma metastasis and prognosis prediction, including MYC, GPNMB, GAB2, and SATB1." (PMID 25116415, 2014). "Our present data demonstrate that at least one of the major causes of senescence in MYC-depleted melanoma cells is the down-regulation of TS- and RR-dependent dNTP pools." (PMID 23249808, 2012). "Simultaneous genetic inhibition of TS and RR in melanoma cells induced DNA damage and senescence phenotypes very similar to the ones caused by MYC-depletion." (PMID 23249808, 2012). "We investigated the development of melanomas and fibrosarcomas in these animals and characterized the properties of c-MYC deficient TAMs." (PMID 23028984, 2012). "The effects of RAF/RAS mutations on the melanoma metabolism include stimulating MYC and HIF1α signaling to promote glycolysis, as well as the inhibition of mitochondrial oxidative phosphorylation (OXPHOS) by repressing MITF and PGC1α, and promoting fatty acid synthesis." (PMID 38397192, 2024). "Notably, we identify a strong association between MYC+ Melanoma (MYC+MEL) and FGFBP2+NKT cells with LN metastasis." (PMID 38065972, 2023). "In addition, a higher percentage of MYC mutations was observed in patients with sinus/nasopharynx melanoma when compared with patients with vulvovaginal melanomas." (PMID 33724703, 2021). "High MYC expression is often associated with tumor metastasis and poor prognosis in melanoma." (PMID 34044811, 2021). "This hypothesis is supported by data from melanoma where tumor development is associated with the expression of BIN(+12) variant which was further demonstrated to be unable to inhibit MYC-mediated malignant transformation." (PMID 30635567, 2019). "In the current study, we demonstrate that MYC-depleted melanoma cells undergo extensive DNA damage that is caused by the underexpression of thymidylate synthase (TS) and ribonucleotide reductase (RR) and subsequent depletion of deoxyribonucleoside triphosphate pools." (PMID 23249808, 2012). "We then compared the protein level of NOLC1 with RCOR1 and MYC in a panel of fourteen melanoma cell lines." (PMID 41227344, 2025). "To test if DANCR is directly regulated by MITF and c-MYC in melanoma we depleted these two transcription factors in multiple human melanoma cell lines using siRNA transfection and measured changes in gene expression using RT-qPCR." (PMID 41336739, 2025). "MITF thus regulates DANCR in a melanoma cell dependent manner whilst c-MYC activates DANCR across melanoma cells." (PMID 41336739, 2025). "In 3 melanoma cell lines (1205Lu, WM793, and A375), NR2F1 expression induced an enrichment in the hallmark gene sets for MYC targets variant 2 and mTORC1 signaling in the presence BRAFi + MEKi compared with treated control cells that did not overexpress NR2F1." (PMID 40955663, 2025). "We classified each cell based on its predominant correlation, finding that few melanocytes in healthy skin exhibited MYC program dominance, whereas most melanomas (10 of 14) contained a population of MYC cells at 5% or greater." (PMID 41405996, 2025). "Unexpectedly, the BRN2-high state is also present in melanocytes, whereas the MYC state is exclusive to melanoma." (PMID 41405996, 2025). "This reactivates PP2A, suppresses Akt and MYC, and significantly reduces melanoma cell viability, inducing apoptosis, and inhibiting migration and invasion." (PMID 41155727, 2025). "While melanocytes share most states, melanoma uniquely acquires the MYC state and transitions more frequently, revealing plasticity as a therapeutic vulnerability." (PMID 41405996, 2025).